CCK (cholecystokinin)
Diseases named in the same sentence as CCK in open-access papers (continued):
Sharing a sentence is not in itself a finding about the gene and the disease.
chronic pancreatitis (9 papers, 2011 to 2025). A chronic inflammatory process causing damage and fibrosis of the pancreatic parenchyma. "Repeated intraperitoneal injections of the cholecystokinin analogue caerulein induces chronic pancreatitis in mice with morphological changes such as loss of acinar cell mass and an increase in pancreatic fibrosis similar to that seen in the human condition." (PMID 22220202, 2011). "In conclusion, molecular cytogenetic and in silico analyses of a deletion of the short arm of chromosome 3 in a patient with AS, seborrheic dermatitis, and chronic pancreatitis have supported previous linkage findings and have implicated CCK as a new candidate gene for AS." (PMID 26523151, 2015). "An anti-inflammatory effect of CCK system blockade has already been demonstrated in a proglumide-treated model of chronic pancreatitis." (PMID 38399359, 2024). "This anti-inflammatory effect of CCK blockade has already been shown in a model of chronic pancreatitis treated with proglumide." (PMID 36559317, 2022). "Camostat mesylate was first approved in Japan 2006 for the treatment of chronic pancreatitis due to its inhibitory effects on cholecystokinin, pro-inflammatory cytokines, and serine proteases in human." (PMID 33641565, 2021). "To evaluate whether tissue stress through chronic pancreatitis could cooperate with Daxx loss to promote tumorigenesis in β cells, we treated DR and Cre-negative littermate control (D) mice with the cholecystokinin analog caerulein." (PMID 35976056, 2022).
Cognitive impairment (9 papers, 2020 to 2025). Abnormal cognition is characterized by deficits in thinking, reasoning, or remembering. "Another clinical study measuring cerebrospinal fluid levels of CCK found that higher CCK was associated with a decreased likelihood of having mild cognitive impairment or AD, suggesting that CCK may serve as a biomarker of neural integrity, and cognitive performance in AD." (PMID 40013092, 2025). "In parallel, our current study proposes CCK administration as a promising approach to induce thalamocortical plasticity in the adult brain, providing a foundation for exploring CCK-based interventions in age-related sensory and cognitive deficits." (PMID 41264484, 2025). "In a follow-up study, the same group reported that the CCK analogue ameliorated cognitive deficits and regulated mitochondrial dynamics by activating the CCKB receptor and the AMPK/Drp1 pathway in APP/PS1 mice." (PMID 40013092, 2025). "CCK has been studied in the context of neurodegenerative diseases such as AD, with a relationship found between higher levels of CCK and reduced probability of mild cognitive impairment and AD." (PMID 39634607, 2024). "Here, we found that surgery/anesthesia‐induced cognitive impairment in aged mice, and significantly decreased the levels of CCK‐8 in the hippocampus, especially in CA1 and DG regions." (PMID 34402181, 2021). "Contrarily, recent studies demonstrated that higher CCK levels are also related to a decreased likelihood of having a mild cognitive impairment and AD symptoms." (PMID 34276354, 2021). "Our findings indicated that CCK‐8 alleviated cognitive impairment and promoted glutamatergic synaptogenesis by inhibiting the induction of A1 reactive astrocytes and the activation of microglia." (PMID 34402181, 2021). "Collectively, these findings suggest that the increase in CCK levels by hop bitter acids containing a β-tricarbonyl moiety leads to vagus nerve activation and improve the cognitive impairment induce by inflammation." (PMID 33208787, 2020). "Finally, we focused only on short‐term postoperative cognitive impairment; however, the effects of CCK‐8 on long‐term cognition in aged mice warrant further study." (PMID 34402181, 2021). "CCK‐8 alleviates postoperative cognitive impairment and promotes glutamatergic synaptogenesis in the hippocampus via inhibition of A1 reactive astrocytes, which may be mediated by inhibition of microglia activation." (PMID 34402181, 2021). "Although several studies have confirmed the involvement of CCK in aging and neurodegenerative disease‐induced memory impairment, the functions of CCK in perioperative cognitive impairment have not yet been reported." (PMID 34402181, 2021). "Hence, given the ability of CCK interneurons that express CB1R to influence SWR, and the role of SWR in memory, our findings support the notion that disrupted hippocampal oscillations are responsible for particular forms of cognitive impairment induced by prenatal THC exposure." (PMID 31982904, 2020).
Constipation (8 papers, 2017 to 2025). Infrequent or difficult evacuation of feces. "Therefore, the improvement in the ENS function through the Urd and AEtLP treatments during C3-deficiency-induced constipation is reflected in the regulation of CCK and gastrin concentrations." (PMID 37958740, 2023). "Previous studies have reported that the concentrations of CCK and gastrin were significantly increased in the Lop-induced constipation model after exposure to spicatoside A as compared to the Lop+Vehicle-treated group." (PMID 34885790, 2021). "Thus, the results of the present study provide the first evidence that the defecation stimulation effects of Pt are strongly correlated with changes in CCK and gastrin concentrations in the Lop-induced constipation model." (PMID 34885790, 2021). "To investigate whether the defecation stimulation effects of TEE are accompanied by alterations in regulating the secretion of GI hormones of constipation rats, we measured the concentrations of CCK, gastrin and SS in the colon homogenate of Lop-induced constipation rats after TEE treatment." (PMID 33626068, 2021). "Studies have reported that GI hormones such as motilin (MTL), cholecystokinin (CCK), gastrin (Gas), and SP are significantly decreased while SS and VIP are increased in constipation-induced rats." (PMID 36145085, 2022). "For example, cholecystokinin (CCK) is known to mediate sensory and motor responses to intestinal distension and is believed to contribute to the symptoms of constipation, bloating, and abdominal pain, while CCK receptor antagonists have been tested in patients with constipation." (PMID 41131424, 2025). "Regulation of gastrointestinal hormones, such as cholecystokinin (CCK), gastrin (GAS), somatostatin (SS) and motilin (MTL), may also be another important mechanism for improving the symptoms of LOP-induced constipation in animal models after ACCE administration." (PMID 35518898, 2019).
cholelithiasis (7 papers, 2021 to 2026). The presence of crystallized deposits forming in the gallbladder or biliary tree, primarily composed of cholesterol, bilirubin, and bile. "Gastrectomy and gastrointestinal reconstruction increase the incidence of cholelithiasis by causing biliary stasis through the sphincter of Oddi, reflux infection, and changes in cholecystokinin secretion." (PMID 40922910, 2025). "Additionally, rapid weight loss reduces the secretion of cholecystokinin, which diminishes gallbladder motility and delays gallbladder emptying, ultimately leading to the formation of cholesterol crystals and cholelithiasis." (PMID 40697657, 2025). "For this reason, in patients undergoing R‐Y surgery, the secretion of cholecystokinin is insufficient, and it is thought that cholelithiasis is likely to occur due to the accumulation of bile." (PMID 40922910, 2025). "Increased cholesterol secretion rate, larger gallbladder size, and decreased cholecystokinin levels without a proportional increase in bile salts in obese individuals have been suggested as possible causes of gallbladder diseases such as cholelithiasis, cholecystitis, and cholesterolosis." (PMID 37113933, 2023). "Gallbladder dyskinesia (GBD) is a functional biliary disorder characterized by biliary colic in the absence of cholelithiasis or mechanical obstruction and is identified by reduced gallbladder ejection fraction (EF) on cholecystokinin (CCK)-stimulated hepatobiliary scintigraphy." (PMID 41918658, 2026).
cholestasis (7 papers, 2014 to 2025). Impairment of the bile flow caused by obstruction within the liver, or outside the liver in the bile duct system. "An intriguing area of study is the role of cholecystokinin (CCK) in mitigating the severity of cholestasis and other TPN associated dysfunctions." (PMID 36364922, 2022). "In summary, CCK remains a promising treatment for TPN associated cholestasis, however further research is necessary to establish the peptide has a definitive treatment." (PMID 36364922, 2022). "High LDL can promote the formation of cholesterol polyps by lowering the sensitivity of the gallbladder to cholecystokinin, which subsequently results in decreased gallbladder contraction, cholestasis, and a relative deficiency of cholic acid." (PMID 33752687, 2021). "This may be because PN bypasses enteral feeding, leading to a lack of food stimulation in the intestines, which reduces the secretion of cholecystokinin, inhibits gallbladder contraction, decreases bile discharge, and causes cholestasis." (PMID 41018060, 2025). "Daily infusions of CCK attenuated the PN-associated cholestasis." (PMID 24719613, 2014). "In human studies, CCK has been assessed in its ability to alleviate cholestasis in neonates." (PMID 36364922, 2022). "The lack of enteral food stimulation may reduce cholecystokinin secretion, decrease gallbladder emptying and bile flow, and increase the risk of cholestasis." (PMID 35186808, 2022). "Therefore, the intact digestive process reconstructed by fistuloclysis could stimulate CCK secretion and further alleviate cholestasis." (PMID 24719613, 2014).
chronic cholecystitis (7 papers, 2017 to 2025). "It is hypothesized that increased CCK production or upregulation of CCK receptors may lead to excessive gallbladder contraction, causing intramural inflammation and a cholecystitis-like presentation." (PMID 40342469, 2025). "Previous authors speculated that the chronic cholecystitis found on pathology could represent mucosal injury from increased intraluminal pressure due to cholecystokinin hypersensitivity." (PMID 30716707, 2019). "In the present study, when GBEF was below 35% on a CCK-provoked HIDA scan, chronic cholecystitis was reported on final histopathology in 93% of cases." (PMID 33569543, 2021). "Of the remaining 15 patients (16.5%), 9 were diagnosed with acute cholecystitis by the HBS protocol, and the other 6 were diagnosed as having chronic cholecystitis by the use of either Morphine Sulfate (MSO4) or Sincalide, a synthetic C-terminal octapeptide of cholecystokinin (CCK-8)." (PMID 33364545, 2020).
epilepsy (7 papers, 2011 to 2025). A brain disorder characterized by episodes of abnormally increased neuronal discharge resulting in transient episodes of sensory or motor neurological dysfunction, or psychic dysfunction. "The Cck (Cholecystokinin) signaling pathway, for example, is inversely associated with pharmacoresistance in epilepsy, because it controls the activity of hippocampal inhibitory interneurons." (PMID 29196444, 2018). "The expression of CCK‐expressing cells in epileptic rats displayed a similar trend in the change of dendritic morphology during epilepsy and after treatment with CBD." (PMID 29574880, 2018). "This outstanding preservation of CB1-expressing cholecystokinin-immunoreactive cells in epilepsy is comparable to the surviving of calbindin-positive interneurons." (PMID 28116310, 2017). "Besides NPY a variety of other parameters of GABA-ergic neurons, e.g., glutamate decarboxylase (GAD1 and 2), somatostatin (SOM) or cholecystokinin (CCK-8) are dynamically altered in animal models of epilepsy." (PMID 36311021, 2022). "Furthermore, our data suggest a neuroprotective role for CBD, since treatment with CBD rescued the morphological pathology of PV‐ and CCK‐expressing interneurons induced by epilepsy." (PMID 29574880, 2018). "Using electrophysiological techniques, we initially investigated whether CBD could alter the epilepsy‐induced synaptic and biophysical properties of pyramidal cells, PV‐ and CCK‐expressing interneurons, in an established rodent model of epilepsy." (PMID 29574880, 2018). "In epilepsy, while a selective decrease of CCK BC terminals have been observed in the CA1, GABABRs expression at CCK axon terminals appears to be increased leading to stronger disinhibitory effects of principal cells potentially promoting seizure generation and the progression of epilepsy." (PMID 28466358, 2017). "In the chronic phase of epilepsy CB1-R-positive (and also CCK-positive) cell bodies were preserved in the dentate gyrus and in the CA1 area, despite the mass principal cell loss." (PMID 22076136, 2011). "Interestingly, while the activation of muscarinic acetylcholine receptors (mAChRs) typically inhibits GABA release from CB1-expressing terminals, mAChR activation can also excite CCK/CB1 co-expressing interneurons, adding complexity to the regulatory mechanisms involved in epilepsy." (PMID 40430045, 2025).
anorexia nervosa (6 papers, 2007 to 2025). A disorder most often seen in adolescent females characterized by a refusal to maintain a minimally normal body weight, an intense fear of gaining weight, a disturbance in body image, and, in postmenarcheal females, the development of amenorrhea. "This CCK “peak” was also found in patients with anorexia nervosa and although the exact cause is unknown, this phenomenon is potentially reversible when the nutritional status is recovered." (PMID 31191339, 2019). "Binge eating excessive amounts of food, as observed in the binge eating disorder, bulimia nervosa, and in binge–purging-type anorexia nervosa, are typically accompanied by decreased CCK release." (PMID 37630700, 2023). "Two studies found higher CCK levels in anorexia nervosa (AN) patients compared to controls, whereas three others did not." (PMID 23349895, 2013). "Despite a number of studies in the past decades, the role of Cholecystokinin (CCK) in anorexia nervosa (AN) has remained uncertain." (PMID 23349895, 2013). "In humans, two studies found higher CCK levels in anorexia nervosa (AN) patients compared to controls, whereas three others did not." (PMID 23349895, 2013). "In anorexia nervosa, the CCK results are ambiguous, which to some extent may be explained by assay differences and small numbers of the mainly young girls who have been studied." (PMID 40557463, 2025). "Our data indicate that CCK-LI release in long-term and severe anorexia nervosa (irrespective of the subtype) is well adapted to the chronic malnutrition and responds normally when stimulated with a standard (test) meal of low volume and caloric content (250 kcal)." (PMID 23349895, 2013).
gallbladder disease (6 papers, 2022 to 2025). "Despite a clear demonstration of CD-related CCK perturbation and gallbladder motor dysfunction, clinical studies focused on gallbladder disease in CD patients are scarce." (PMID 36297063, 2022). "Thus, in an attempt to avoid gallbladder disease, we cannot conclude that fat should be restricted in healthy dogs, since ingestion of fatty acids appears to be important in the stimulation of cholecystokinin secretion, neither can it be affirmed that cholesterol should be restricted in dog diets." (PMID 39852880, 2024).
gastric cancer (6 papers, 2014 to 2022). A primary or metastatic malignant neoplasm involving the stomach. "In this study, we further investigated the effects of gastrin/CCK-BR autocrine/paracrine signaling on cell invasion and metastasis and underlying mechanisms in gastric cancer." (PMID 34976177, 2022). "In the GI tract, GPR35 has been linked to the development of gastric cancer, but it also actively modulates energy balance through the secretion of peptide hormones, such as cholecystokinin (CCK)." (PMID 34497585, 2021). "According to a previous study, gastrin and cholecystokinin were associated with NETs; this resulted in tissue growth in the gastrointestinal tract and carcinogenesis that led to colorectal and gastric cancers." (PMID 25427657, 2014). "In conclusion, the present findings revealed a gastrin/CCK-BR autocrine/paracrine signaling loop in gastric cancer cells, which plays a significant role in the invasion and metastasis of cancer cells by promoting MMP-2 and VEGF expression." (PMID 34976177, 2022). "After the stable cells overexpressing gastrin were exposed to proglumide (5 mmol/L) for 48 h, both cell growth rate and colony formation rate were significantly decreased, suggesting that the gastrin/CCK-BR loop is involved in gastric cancer cell growth." (PMID 34976177, 2022). "In this study, we established six gastric cancer cell lines with enhancement or inhibition of gastrin/CCK-BR signaling by overexpression or knockdown of gastrin in cells to confirm that a functional gastrin/CCK-BR loop existed in gastric cancer cells." (PMID 34976177, 2022). "Although this investigation was performed in immune competent mice with syngeneic murine tumors, the results of the CCK-BR immunoreactivity on the human gastric cancer array support the important translational and clinical relevance of this work." (PMID 34926305, 2021). "In the current investigation, we studied the role of the gastrin-CCK-BR pathway in vitro and in vivo as well as the expression of the CCK-BR in a human gastric cancer tissue array." (PMID 34926305, 2021). "Immunocytochemistry revealed endogenous gastrin peptide expression in both NCC and YTN gastric cancer cells suggesting that these gastric cancer cells produce their own gastrin peptide to stimulate growth via the CCK-BR in an autocrine fashion." (PMID 34926305, 2021). "Human gastric cancer epithelial cells were positive for CCK-BR immunoreactivity implying that the administration of PAS to human subjects would also decrease activation of this receptor by neutralizing gastrin." (PMID 34926305, 2021). "In the current investigation, we demonstrated using two murine gastric cancer cell lines and a human tissue microarray that the gastrin: CCK-BR signaling pathway is important in stimulating growth of gastric cancer." (PMID 34926305, 2021). "Previous study has reported that gastrin acting on CCK-BR induces cyclooxygenase-2 expression through JAK2/STAT3/PI3K/Akt pathway in human gastric cancer cells." (PMID 27518872, 2016). "Moreover, previous research proved that the gastrin and CCK-BR loop blockage inhibited gastric cancer cells proliferation." (PMID 27518872, 2016). "However, whether the gastrin/CCK-BR axis is crucial for the invasion and metastasis of gastric cancer cells remains unclear." (PMID 34976177, 2022). "We found that both murine gastric cancers (YTN and NCC) expressed CCK-BRs and when YTN tumor bearing mice were treated with a gastrin vaccine, the tumor growth rate and metastases significantly decreased." (PMID 34926305, 2021). "CCK and CCK1R might play a more important role than for gastrin and CCK2R in gastric cancers." (PMID 32210918, 2020).